INS (insulin)
Diseases named in the same sentence as INS in open-access papers (continued):
Sharing a sentence is not in itself a finding about the gene and the disease.
Hypoglycemia (continued). "Regular insulin in multiple doses is important for achieving strict glycemic control for T1DM, but short-acting insulin analogues may be better in reducing hypoglycemia and postprandial glucose levels." (PMID 30622653, 2019). "Insulin load, performed as part of the insulin tolerance test at the age of 10 weeks old (in order to verify the development of metabolic alteration at the beginning of SSE intervention), induced severe hypoglycemia." (PMID 31847157, 2019). "This is not to mention the additional costs for the rapidacting insulin and potential ER visits for severe hypoglycemia." (PMID 31404422, 2018). "While not unexpected that insulin secretion is influenced by the presence of a GCK mutation, to our knowledge, this is the first time that a different effect on endogenous insulin secretion between GCK-MODY and T2D has been demonstrated in vivo during acute hypoglycemia." (PMID 30146176, 2018). "A post-hoc analysis of SAVOR-TIMI 53 trial found that hypoglycemia rates (any or major) were increased with saxagliptin in patients taking sulfonylureas, not in those taking insulin." (PMID 29787616, 2018). "For the individuals taking insulin without oral agents who returned with hypoglycemia, all 4 individuals were taking long-acting insulin [insulin glargine (Lantus) or insulin detemir (Levemir)] with or without non-long-acting insulin (5.3% [CI 2.1–12.7%])." (PMID 29799604, 2018). "Optimally, insulin aims to create a normal glycemic profile as possible without unacceptable weight gain or chances of hypoglycemia." (PMID 29527102, 2018). "Rates of severe hypoglycemia are more common among older adults and those with chronic conditions, such as chronic kidney disease, CVD, HF and depression, as well as among those who are on insulin or take secretagogues." (PMID 29960591, 2018). "Although greater amounts of insulin were used with the PoIIT, no recipients developed clinically relevant hypoglycemia." (PMID 30390037, 2018). "Meta-analyses of clinical trials reported efficacy outcomes with basal insulin analogues to be mostly non-inferior or better than with other insulins, while the incidence of hypoglycemia (in particular nocturnal) was reduced." (PMID 29460260, 2018). "Referred episodes of hypoglycemia were high, in both T1DM and T2DM insulin users." (PMID 30479669, 2018). "No return visits for hypoglycemia were identified among the 68 individuals who took short acting or intermediate acting insulin without oral agents or long acting insulin." (PMID 29799604, 2018). "Receiving an insulin bolus did not result in a higher incidence of hypoglycemia (p = 0.64) or hypokalemia (p = 0.65) within 4 h of DKA protocol initiation." (PMID 30544554, 2018). "This drug delivery method increases CSF concentrations of insulin in the absence of peripheral side effects such as hypoglycemia." (PMID 29743868, 2018). "Our results are well aligned with the expectations of physicians, who aimed to achieve good glycemic control without hypoglycemia or weight gain when initiating persons with T2DM on basal insulin analogues." (PMID 29460260, 2018). "A previous study used short hairpin RNA-knockdown of VMN GCK in rats, reporting increased epinephrine responses to non-clamped (insulin-bolus induced) hypoglycemia." (PMID 30146176, 2018). "From a post hoc graphical assessment (data not shown), no meaningful pattern between hypoglycemia rate and insulin dose was revealed." (PMID 29760944, 2018). "Basal bolus regimens, with IDeg as a basal insulin, helps in achieving optimal glycemic controls with minimal or no episodes of hypoglycemia." (PMID 30069184, 2018). "Together, these data show that the hypoglycemia in infected Adx mice is not reversed by administration of glucose, by blocking insulin release with clonidine or by neutralizing TNF-α." (PMID 30375380, 2018).
Hypoglycemia (continued). "Prevention of hypoglycemia, as measured by CGM, was noted when the basal rate in insulin pump users was reduced by at least 80%, beginning at the start of exercise and lasting two hours following a 30-min aerobic exercise protocol (75% of VO2peak) performed 3 h after lunch." (PMID 30081478, 2018). "Reasons for not increasing IGlar dose to reach HbA1c goal, particularly for participants without hypoglycemia, were not assessed in these trials, and insulin resistance was not measured." (PMID 29760944, 2018). "In small, single-centre studies, incretin-based therapies lowered blood glucose and reduced insulin administration without increasing the incidence of hypoglycaemia." (PMID 30428906, 2018). "The following factors were associated with nonadherence: lack of planning of daily activities (46.1%), fear of hypoglycemia (41%), economic factors (15.4%), and number of insulin applications (2.31 versus 1.76 applications per day)." (PMID 30116737, 2018). "No hypoglycemia events (glucose < 3.3 mmol/l) were recorded: when basal insulin was reduced: 1/ by 50% or 80% during moderate exercise (50% VO2peak) or 2/ by 80% or pump stopped for the intense exercise sessions (75%VO2peak)." (PMID 30713524, 2018). "In the presented study, the insulin dose was significantly higher among patients treated with human insulin compared to the ones using insulin analogue; however, it affected neither hypoglycemia rate nor BMI." (PMID 29755520, 2018). "In support of increased insulin levels under non-stimulatory conditions, random postprandial glucose measurements indicated life-long hypoglycemia in Ins-c-Myc mice." (PMID 29396395, 2018). "The review of HbA1c, insulin doses, and safety parameters (hypersensitivity event and hypoglycemia) in these participants did not suggest negative effects of high AIA titers on these measures in either treatment group." (PMID 29355435, 2018). "She no longer had fasting hypoglycemia but had persistent reactive hypoglycemia, managed with dietetic support in combination with acarbose (α-glucosidase inhibitor) to limit postprandial insulin secretion." (PMID 30085133, 2018). "This drug delivery method increases cerebrospinal fluid concentrations of insulin in the absence of peripheral side effects, such as hypoglycemia." (PMID 29743868, 2018). "Together, these data indicate that inappropriate release of insulin is not the driver of hypoglycemia in the Adx mice." (PMID 30375380, 2018). "GLP-1 analogues can be added to insulin therapy if glycemic goals are not achieved with reasonably high doses of insulin or if unacceptable weight gain or hypoglycemia occurs." (PMID 29527102, 2018). "Few patients (dapagliflozin, n = 3; placebo, n = 3) experienced nonsevere symptomatic hypoglycemia, and all of these patients were in the insulin stratum." (PMID 30222367, 2018). "Some patients with previous hypoglycemia episodes were prescribed NPH insulin, which seems to be contradictory since this medication would not be the preferable treatment for patients with recurrent hypoglycemia episodes." (PMID 29713649, 2018). "For example, in a South African study, doctors did not know how to properly use/prescribe insulin and had fears related to the induction of hypoglycemia." (PMID 29670916, 2018). "In this study, we have investigated symptoms and hormonal responses to insulin-induced hypoglycaemia in people with IAH and combined these data with data from non-invasive sensors, with the aim to evaluate the potential for detection of hypoglycaemia." (PMID 30283093, 2018). "The factors significantly associated with better adherence were adequate economic resources, planning of daily activities around insulin application, lack of fear of hypoglycemia, and fewer insulin applications per day." (PMID 30116737, 2018). "Plasma insulin levels were not increased in PcAS-infected Adx mice compared to Sham mice, but were not suppressed either, despite the severe hypoglycemia." (PMID 30375380, 2018).
Hypoglycemia (continued). "None of the hypoglycemia episodes has been reported to be due to injecting insulin then not eating the planned meal." (PMID 29682577, 2018). "In low fat-fed mice, we found that 50 mg/kg but not 30 mg/kg STZ induced severe hypoglycemia following i.p. insulin administration." (PMID 29854823, 2018). "This was in comparison to 21/52 (40%) of those insulin-treated patients without a documented hypoglycaemia episode, p = 0.008." (PMID 28918198, 2018). "As part of the same study, basal insulin suspension during circuit training (which counts as HIIE) resulted in less variability in interstitial glucose during the recovery period, and less time spent in hypoglycemia." (PMID 30081478, 2018). "Insulin doses were higher but hypoglycemia yearly event rates were lower in nonresponders compared with responders at study endpoint." (PMID 29760944, 2018). "In another report, when compared with individuals with normal awareness of hypoglycaemia in a UK clinic, those individuals with IAH were significantly less likely to follow advice on insulin regimen adjustment, presumably often focusing on hypoglycaemia avoidance." (PMID 29423581, 2018). "Insulin lispro was not inferior to insulin aspart in HbAlc, total daily insulin dose, weight change, and incidence and rates of hypoglycemia." (PMID 29780415, 2018). "In general, SGLT2i drugs do not induce hypoglycemia because they increase plasma glucagon concentrations and decrease plasma insulin concentrations." (PMID 29511288, 2018). "In one study, 93% of patients was using insulin and only 1 patient did not have documented hypoglycaemia in the pre-hospital context." (PMID 29685177, 2018). "With respect to the experience associated with insulin injection, the nonadherent group reported that fear of hypoglycemia, pain, bruising, embarrassment, and injecting insulin were considered the most difficult parts of treatment." (PMID 30116737, 2018). "One case report of metformin toxicity reported recurrent hypoglycemia where co-ingestion of sulfonylurea or insulin use has been ruled out by extensive laboratory tests." (PMID 30119705, 2018). "The results of the clinical trials indicate that despite increasing meal insulin boluses, overestimation of the meal category did not result in increased time spent in hypoglycemia." (PMID 29422651, 2018). "Although, the severity of hypoglycemia symptoms is reportedly not proportional to the tumor burden, we found a positive correlation between tumor size and insulin and C-peptide level." (PMID 30522468, 2018). "Reports have highlighted the importance of hypoglycemia, defined as glucose concentrations less than 4.0 mmol/L, in intensive insulin therapy compared to conventional therapy with or without the use of an insulin pump." (PMID 28271075, 2017). "Rosiglitazone acts by increasing insulin sensitivity rather than increasing insulin levels, does not induce hypoglycaemia, and has an established safety profile in adults." (PMID 28535809, 2017). "In paediatric intensive care, use of CGM to guide frequency of blood glucose measurements in a trial of insulin and tight glycaemic control did not prevent severe hypoglycaemia." (PMID 29051825, 2017). "It is interesting to note here that the nocturnal glycemic variability profiles demonstrated that those without nocturnal hypoglycemia showed a flat pattern with insulin degludec." (PMID 28683068, 2017). "Other studies have reported that those on insulin exercised lesser due to the fear of hypoglycemia and were more likely to be non-compliant to insulin injections as it causes discomfort and interferes with their daily activities." (PMID 28362861, 2017). "Since systemic insulin administration in non-diabetic subjects produces hypoglycemia, the approach that has been promoted to achieve this goal is intranasal insulin administration, which involves bulk flow through the olfactory bulb into the brain." (PMID 28515688, 2017).
Hypoglycemia (continued). "The improvement in glucose control was achieved without increased maternal hypoglycaemia, gestational weight gain, or total daily insulin dose, but with an increase in the rate of change in glucose concentrations." (PMID 28923465, 2017). "They approximate the upper and lower limits, respectively, of the non-diabetic glycaemic threshold for symptoms of insulin-induced hypoglycaemia." (PMID 27872948, 2017). "Levels of MDA and ISO-8 were unaltered during HI-infusion, suggesting that, in contrast to acute and recurrent insulin-induced hypoglycaemia, lipid peroxidation is not increased in the brain during chronic blood glucose lowering." (PMID 28421113, 2017). "In the case of IGlar, this is based on postmarketing data; for IDet, an RCT has been performed, demonstrating significantly lower FPG and non-inferior HbA1c in late pregnancy and similar rates of hypoglycaemia compared with NPH insulin." (PMID 28100192, 2017). "Significant reductions in FPG and PPG were observed, without encountering any side effects as hypoglycaemia or changes in basal plasma insulin and C-peptide levels." (PMID 28724331, 2017). "HbA1c and DTSQ evaluation were the outcome variables of the study, similar to our trial, but the PHR-based collection of hypoglycemia data, which is important for insulin users, was not attempted in the previous study." (PMID 28720103, 2017). "It is well established that pregnancy does not alter the ability of hypoglycemia to suppress insulin secretion; therefore, the diagnosis of endogenous hyperinsulinism can be made by prolonged fasting as in the non-pregnant state." (PMID 28427440, 2017). "Major barriers to insulin use reported by providers included lack of refrigeration, lack of glucose test strips, and fear of hypoglycemia." (PMID 28245810, 2017). "In fact, i.v. infusion of glucose does not stimulate insulin secretion in comparable amounts, nor is it followed by hypoglycemia." (PMID 28185153, 2017). "We determined the incidence of hypoglycemia and severe hypoglycemia (blood glucose <70 or ≤40 mg/dl, respectively) in a cohort of AKI and non-dialysis dependent CKD patients who received an intravenous infusion of insulin plus glucose to treat hyperkalemia." (PMID 28245289, 2017). "This is consistent with earlier findings that DPP-4 inhibitors do not increase hypoglycemia rates, even though they increase insulin secretion in a glucose-dependent manner." (PMID 29037205, 2017). "Our current data shows that SGLT2i as an insulin adjunct in T1DM does not increase the incidence of total AEs, hypoglycemia, or genital and urinary infections, however, the risk of DKA should be carefully monitored." (PMID 28276512, 2017). "Insulin has good glucose-lowering effects, but can lead to hypoglycaemia if not carefully prescribed according to the patient’s lifestyle; therefore, its therapeutic effect should be carefully evaluated." (PMID 29061170, 2017). "Being devoid of hypoglycaemia and other peripheral metabolic effects, which limited the use of the systemic administration of insulin in non-diabetic patients, makes it a preferable way to delivery insulin into the brain." (PMID 28382978, 2017). "The glucose dependency of both the insulin stimulation and the glucagon inhibition is important clinically, as it means that hypoglycaemia does not normally occur during therapy with GLP-1 analogues." (PMID 28551699, 2017). "In the TQ group, serum glucose, HbA1c, and insulin levels were non-significantly different from the control because TQ is a normoglycemic compound that induces hypoglycemia in hyperglycemic state." (PMID 28448463, 2017). "In the multivariate linear regression analysis, T2DM patients without insulin treatment showed a significantly lower hypoglycemia frequency perception compared with insulin-treated LADA subjects (p = 0.006)." (PMID 29062603, 2017).
Hypoglycemia (continued). "The incidence of hypoglycemia is higher in patients with DKD than those without DKD, probably due to the reduction in insulin requirement associated with renal insufficiency." (PMID 28355264, 2017). "We could not find any genetic association between PD and hypoglycemia, nor can we explain the possible cause of hypoglycemia in our patient, because she was not taking any concurrent medicine, including SSRIs, which could have been a cause of increased insulin sensitivity." (PMID 28148284, 2017). "Like any neonatal hypoglycemia, treatment with glyburide resulted in an increase in the incidence of severe neonatal hypoglycemia compared to treatment with insulin; however, the difference was not statistically significant." (PMID 28771572, 2017). "Patients with hypoglycemic excursions received higher insulin doses prior to rewarming than those without hypoglycemia (16.2 versus 2.1 units/hr, p = 0.03)." (PMID 29075530, 2017). "Although late-onset hypoglycemia has been suggested to occur by replenishing of the stored muscle glycogen and by a sustained increase in tissue sensitivity to insulin, its mechanism has not been explored." (PMID 28570686, 2017). "There were no episodes of severe hypoglycaemia, but metformin and insulin gave superior glycaemic control to metformin and glibenclamide, with fewer blood glucose readings <3.5 mmol/l (median [IQR] difference/woman/week of treatment 0.58 [0.03–1.87])." (PMID 28938877, 2017). "The type and duration of action of insulin does not seem to affect the CV outcome; however it does impact on rates of hypoglycemia." (PMID 29270438, 2017). "The primary outcome will be the proportion of patients who reach an optimal insulin dose within 12 weeks of study enrollment, without severe hypoglycemia or unscheduled clinic visits." (PMID 28720103, 2017). "According to the current guidelines, switching from human insulin to insulin glargine should be considered if an individual has hypoglycaemia or fails to reach the target glucose level." (PMID 28573394, 2017). "The frequency of hypoglycemia did not significantly differ depending on the timing of the insulin injection (P = 0.16; Fisher’s exact test)." (PMID 28683068, 2017). "The relationship between SHR and a complicated AMI was independent of diabetic status, intensive insulin therapy, sex and hypoglycemia." (PMID 29233143, 2017). "The present study investigated how the brain of nondiabetic rats copes with chronic insulin-induced hypoglycaemia for up to eight weeks." (PMID 28421113, 2017). "The use of optimised infusion line with a dedicated insulin infusion line did not reduce glycaemic variability but minimised the incidence of hypoglycaemia events." (PMID 28699150, 2017). "Only a minority of pregnant women (<20%) were using pumps with insulin suspend features, so this alone does not explain the reduced incidence of maternal hypoglycaemia." (PMID 28923465, 2017). "Although the frequency of neonatal hypoglycaemia and neonatal hyperbilirubinaemia tended to be higher in the insulin-group, these differences were not statistically significant." (PMID 27680327, 2016). "In our study we conducted a within subject analysis, the intensity of the exercise and degree of hypoglycemia was slightly more vigorous, no insulin was infused during the exercise, and in Arm 2 there was no dextrose infused during the exercise period." (PMID 27597762, 2016). "Infants of metformin group had a lower rate of hypoglycemia compared with infants of insulin group with no more neonatal outcomes." (PMID 27597988, 2016). "There was no increase in the incidence of hypoglycaemia despite half of the patients werepre-treated with insulin, renal impairment, urinary tract infections, volume-related side effects, bone fractures, orthromboembolic events." (PMID 27071968, 2016).